MTA1 (metastasis associated 1)
Description:
Transcriptional coregulator which can act as both a transcriptional corepressor and coactivator. Acts as a component of the histone deacetylase NuRD complex which participates in the remodeling of chromatin. In the NuRD complex, regulates transcription of its targets by modifying the acetylation status of the target chromatin and cofactor accessibility to the target DNA. In conjunction with other components of NuRD, acts as a transcriptional corepressor of BRCA1, ESR1, TFF1 and CDKN1A. Acts as a transcriptional coactivator of BCAS3, and SUMO2, independent of the NuRD complex. Stimulates the expression of WNT1 by inhibiting the expression of its transcriptional corepressor SIX3 (By similarity). Plays a role in the regulation of the circadian clock and is essential for the generation and maintenance of circadian rhythms under constant light and for normal entrainment of behavior to light-dark (LD) cycles (By similarity). Positively regulates the CLOCK-BMAL1 heterodimer mediated transcriptional activation of its own transcription and the transcription of CRY1 (By similarity). Regulates deacetylation of BMAL1 by regulating SIRT1 expression, resulting in derepressing CRY1-mediated transcription repression (By similarity). With TFCP2L1, promotes establishment and maintenance of pluripotency in embryonic stem cells (ESCs) and inhibits endoderm differentiation (By similarity). [Isoform Short]: Binds to ESR1 and sequesters it in the cytoplasm and enhances its non-genomic responses.
Tractability: Small molecule: a structure with a bound ligand is known. PROTAC: UniProt records ubiquitination sites on it; ubiquitination databases record sites on it; its protein half-life has been measured.
Gene: Protein-coding gene on chromosome 14 (105,419,808 to 105,470,737, forward strand). Ensembl gene ENSG00000182979.
Subcellular location: Nucleus; Cytoplasm (Isoform Short); Nucleus (Isoform Long); Nucleus envelope; Cytoplasm; Cytoplasm, cytoskeleton
Subcellular location (Human Protein Atlas): Nucleoplasm; Cytosol
Pathways (Reactome):
Gene expression (Transcription): ERCC6 (CSB) and EHMT2 (G9a) positively regulate rRNA expression; RNA Polymerase I Transcription Initiation; Regulation of endogenous retroelements by KRAB-ZFP proteins; Regulation of endogenous retroelements by Piwi-interacting RNAs (piRNAs)
Chromatin organization: HDACs deacetylate histones; Interaction of NuRD complexes with transcription factors; NuRD complex assembly
Developmental Biology: Differentiation of naive CD4+ T cells to T helper 2 cells (Th2 cells); Transcriptional regulation of brown and beige adipocyte differentiation by EBF2
Disease: Potential therapeutics for SARS
Metabolism of proteins: SUMOylation of transcription factors
Signal Transduction: Regulation of PTEN gene transcription
Gene Ontology:
Molecular function: protein binding; RNA polymerase II cis-regulatory region sequence-specific DNA binding; RNA polymerase II-specific DNA-binding transcription factor binding; transcription coactivator activity; transcription corepressor activity; histone deacetylase binding; chromatin binding; sequence-specific DNA binding
Biological process: chromatin remodeling; double-strand break repair; negative regulation of gene expression, epigenetic; positive regulation of protein autoubiquitination; proteasome-mediated ubiquitin-dependent protein catabolic process; response to ionizing radiation; circadian regulation of gene expression; entrainment of circadian clock by photoperiod; locomotor rhythm; negative regulation of DNA-templated transcription; negative regulation of transcription by RNA polymerase II; positive regulation of DNA-templated transcription; regulation of cell fate specification; regulation of stem cell differentiation; signal transduction; regulation of DNA-templated transcription
Cellular component: cytoplasm; cytosol; microtubule; nuclear envelope; nucleoplasm; nucleus; NuRD complex; cytoskeleton
Genetic constraint (gnomAD): Loss-of-function variants: 12 observed, 92.96 expected, observed/expected ratio (o/e) 0.13, 90% interval 0.082 to 0.21. The upper end of that interval is the gene's LOEUF score, 0.21, which puts it in group 1 of 6, group 1 being the genes least tolerant of losing a copy. Missense variants: 688 observed, 991.43 expected, observed/expected ratio (o/e) 0.69, 90% interval 0.65 to 0.74. Synonymous variants: 427 observed, 413.69 expected, observed/expected ratio (o/e) 1.03, 90% interval 0.95 to 1.12.
Homologues: Orthologues: macaque MTA1 (98% identical), chimpanzee MTA1 (97% identical), dog MTA1 (97% identical), pig MTA1 (96% identical), guinea pig MTA1 (95% identical), rat Mta1 (95% identical), mouse Mta1 (95% identical), tropical clawed frog mta1 (86% identical), zebrafish mta1 (69% identical), Drosophila melanogaster MTA1-like (53% identical). Paralogues in human: MTA2 (59% identical), MTA3 (58% identical), MIER3 (16% identical), MIER2 (16% identical), MIER1 (13% identical).
Diseases named in the same sentence as MTA1 in open-access papers:
MTA1 is named in the same sentence as 109 diseases in open-access papers, as found by Europe PMC text mining. Sharing a sentence is not in itself a finding about the gene and the disease. The quoted sentences say what the papers report.
breast carcinoma (73 papers, 1999 to 2025). "Western blotting showed that overexpression of TRIM21 in breast cancer cells caused a diminishing in the protein level of MTA1, whereas TRIM21 knockdown increased it." (PMID 39154024, 2024). "The 5-ethynyl-2′-deoxyuridine (EdU) results showed that MTA1 knockdown or MTA3 overexpression caused a significant decrease in EdU-labeled breast cancer cells, and MTA1 overexpression or MTA3 knockdown caused the opposite effect." (PMID 39154024, 2024). "They demonstrated that miR-421 suppresses breast cancer metastasis by directly inhibiting the expression of Metastasis Associated 1 (MTA1)." (PMID 37108716, 2023). "We further confirmed that the level of MTA1 was associated with the response of breast cancer patients to mTOR inhibitors." (PMID 37442756, 2023). "This breast cancer cell line is often associated with metastasis-associated proteins (MTA) MTA1 and MTA2 that depict overexpression or reduced expression to contribute to the metastasis of the ZR-75-30 breast cancer cell line." (PMID 38137912, 2023). "RUNX2, a gene most associated with cartilage production, has been linked to pancreatic cancer and to breast cancer progression through modulation of MicroRNAs and the metastasis-associated 1 (MTA1)/NuRD complex." (PMID 37895248, 2023). "O-GlcNAc modification of Metastasis Associated 1 (MTA1) results in increased resistance to genotoxicity in breast cancer." (PMID 37838167, 2023). "MTA1 was first reported as a metastasis-associated molecule in breast cancer, and then, the functions and tumorigenic potential of MTA1 were gradually recognized." (PMID 35350571, 2022). "This work investigated the inhibitory properties of palmatine on the metastatic colonization of breast cancer cells in the lungs and further explored the modulating activity of palmatine on a metastasis-related gene, the metastasis-associated protein 1 (MTA1)." (PMID 35496301, 2022). "Another study found that exosomes were able to mediate membrane transport of metastasis associated protein 1 (MTA1) in breast cancer cells, which had a positive regulatory effect on hypoxia and estrogen signaling." (PMID 34500436, 2021). "In line, tamoxifen-resistant breast cancer cells display high autophagy activation combined with overexpression of metastasis-associated 1 (MTA1)." (PMID 32878084, 2020). "As the first member of the MTA family, MTA1 has been linked to breast cancer metastasis since its discovery, and its crucial role in carcinogenesis and cancer metastasis has been revealed by important studies." (PMID 30642362, 2019). "Elevated cyclinD1 can be downregulated by metastasis associated-1 knockdown to inhibit the cell proliferation and invasion of breast cancer." (PMID 31934637, 2019). "We found that MTA1 overexpression in breast tumors (n = 37) associates (P = 0.024540) with a poor disease-specific survival (HR[95% CI] = 1.54[0.89–2.64]) of breast cancer patients (n = 37)." (PMID 28393842, 2017). "Metastasis-associated protein 1 (MTA1) MTA1 overexpression correlates significantly with tumor grade and angiogenesis in human breast cancers." (PMID 29254284, 2017). "The MTA1 gene has been found to be associated with many tumors, including esophageal carcinoma, thymoma, ovary cancer, and breast cancer." (PMID 23227138, 2012). "MTA1(metastasis associated-1) is a tumor metastasis associated candidate gene and overexpression in many human tumors, including breast cancer." (PMID 21595884, 2011). "The most intriguing of these was the amplification of MTA 1 in SU-2 (metastasis associated 1), a gene previously found to be closely related to the recurrence and metastasis of breast cancer, osteosarcoma and other malignances." (PMID 18940013, 2008). "The MTA1 gene is a recently identified novel candidate breast cancer metastasis-associated gene which has been implicated in the signal transduction or regulation of gene expression." (PMID 10206283, 1999).
breast carcinoma (continued). "MTA1, which presented the third most downregulated protein-coding gene in the RNA-seq analysis and which codes for the metastasis-associated 1 protein, is, as the name already implies, linked to epithelial-mesenchymal transition, invasion, and metastasis, amongst others in breast cancer." (PMID 37803350, 2023). "In addition, metastasis-associated 1 protein, which has been implicated in breast tumorigenesis and metastasis, is upregulated in Tam-resistant breast cancer cells." (PMID 37575061, 2023). "In our attempt to better understand FOXP3’s inhibitory effect on breast cancer metastasis, we found that MTA1, which is associated with breast cancer metastasis, may be a downstream molecule of FOXP3." (PMID 34307133, 2021). "MTA1, a founding member of the metastasis-associated protein family, is first segregated from breast cancer cells, which is up-regulated in lots of types of tumors, such as breast cancer, ovarian cancer, colorectal cancer, pancreatic cancer and myeloma." (PMID 33282725, 2020). "The regulation of DNMT3a by MTA1 may be clinically relevant as low and high levels of DNMT3a and MTA1, respectively, may be associated with a poor survival of patients not only with breast cancer but also in other cancers." (PMID 28393842, 2017). "The Western blot results showed that leptin-induced MTA1 upregulation was suppressed by all these inhibitors, confirming that leptin regulates MTA1 expression via the Ob-R/STAT3 signaling pathway in breast cancer cells." (PMID 40565190, 2025). "This study aimed to clarify the mechanism by which leptin and MTA1 interact to induce VM in breast cancer cells, thereby providing new insights into the roles of leptin and MTA1 in tumor progression." (PMID 40565190, 2025). "Studies have shown that RUNX2 drives the progression and bone metastasis of breast cancer by forming the NuRD (MTA1)/CRL4B complex, which represses the transcription of genes critical for cell growth, EMT, and invasion." (PMID 40287769, 2025). "This study investigated the role of MTA1 in the relationship between leptin and VM in human breast cancer cells." (PMID 40565190, 2025). "In breast cancer, MTA1 has been identified as a pivotal factor, enhancing tumor cell invasiveness and promoting metastasis." (PMID 40565190, 2025). "This study aimed to clarify the mechanisms by which leptin and MTA1 interact to drive VM in breast cancer cells." (PMID 40565190, 2025). "The overexpression of MTA1, achieved using the CRISPR activation plasmid, significantly promoted VM formation, indicating that MTA1 is pivotal in facilitating VM in breast cancer cells." (PMID 40565190, 2025). "Leptin significantly upregulated the mRNA expression of MTA1 in both breast cancer cell lines, indicating regulation at the transcriptional level." (PMID 40565190, 2025). "The qPCR and Western blot analysis revealed a positive correlation between MTA1 expression and leptin treatment in both breast cancer cell lines." (PMID 40565190, 2025). "MTA1 knockdown decreased the frequency of tumor-initiating cells and significantly inhibited the growth of breast cancer." (PMID 39154024, 2024). "MTA1 overexpression or MTA3 knockdown increased colony numbers with the comparison of vector group or shScramble (shSCR), whereas MTA1 knockdown or MTA3 gain-of-function decreased this effect in breast cancer cells." (PMID 39154024, 2024). "MTA1-overexpression promoted the invasiveness of breast cancer cells, while overexpression of MTA3 or TRIM21 restored it to normal levels." (PMID 39154024, 2024). "Migration assays revealed that MTA1 overexpression or MTA3 knockdown resulted into an increase in the migration of breast cancer cells, whereas MTA1 knockdown or MTA3 overexpression induced the opposite effect." (PMID 39154024, 2024). "Our findings showed that the hyperactivation of MTA1 in breast cancer cells drives EMT and cancer stemness." (PMID 39154024, 2024).
breast carcinoma (continued). "The frequency of breast cancer stem cells was obviously higher in the MTA1 overexpression group with the comparison of control group." (PMID 39154024, 2024). "Conversely, MTA3 inhibited MTA1 transcription and TRIM21 regulated MTA1 protein stability in breast cancer." (PMID 39154024, 2024). "Transfection of FLAG-ERα contributed to the upregulated expression of TRIM21 and MTA3 and led to the decreased expression of MTA1 in breast cancer cells." (PMID 39154024, 2024). "Our results add to sights of the complexity of EMT and stemness regulatory networks and suggest that MTA1 is a potential biomarker for breast cancer diagnosis and prospective therapeutic target." (PMID 39154024, 2024). "MTA1 overexpression or MTA3 knockdown promoted breast cancer invasion, whereas knockdown of MTA1 or MTA3 overexpression had the opposite effect." (PMID 39154024, 2024). "The EdU assays in breast cancer cells showed that the decrease in proliferation mediated by MTA1 knockdown was reversed by MTA3 or TRIM21 knockdown." (PMID 39154024, 2024). "Gene Expression Omnibus (GEO) datasets analysis indicated that MTA1 expression was upregulated in breast cancer, MTA3 expression was decreased in breast cancer." (PMID 39154024, 2024). "The findings indicated that MTA1 expression was significantly upregulated in breast cancer tissues compared to that in normal tissues, whereas MTA3 and TRIM21 were the opposite." (PMID 39154024, 2024). "Recent studies have identified the crucial roles of Focal Adhesion Kinase (FAK), VEGF and MTA1 in the progression of breast cancer, which has shed new light on this issue." (PMID 39355129, 2024). "Our study identified multiple regulators of breast cancer stemness and showed that MTA1 influences the cancer stem-like state by interacting with EMT and inhibiting the expression of MTA3 and TRIM21." (PMID 39154024, 2024). "The results demonstrated that MTA1 expression was significantly increased in breast cancer tissues, while MTA3 expression was higher in adjacent tissues." (PMID 39154024, 2024). "We conducted RNA-seq on MCF-7 cells with MTA1 knockdown to investigate its role in regulating breast cancer malignancy." (PMID 39154024, 2024). "Growth curve analysis showed that MTA1 significantly promoted breast cancer cell growth, whereas MTA3 inhibited cell growth." (PMID 39154024, 2024). "Our findings revealed that TRIM21 affects the stability of MTA1 to hinder breast cancer proliferation, invasion, EMT, and cancer stemness and synergizes with MTA3 to maintain epithelial homeostasis." (PMID 39154024, 2024). "We found that the cytoplasmic level of MTA1 was significantly negatively correlated with the response of breast cancer patients to mTOR inhibitors." (PMID 37442756, 2023). "We detected significantly upregulated expression of CXXC5, CUL4B, or MTA1 in breast carcinoma samples compared with that in normal tissues, and their expression levels increased with the histological grades of the tumor specimens." (PMID 36539038, 2023). "MTA1 has also been identified in breast cancer-derived Evs, and it was confirmed to dampen estrogen signaling, as observed after stimulating breast cancer cells with 17β-estradiol." (PMID 38087360, 2023). "The expression of CXXC5, CUL4B, and MTA1 increased during the occurrence and development of breast cancer, and correspondingly, TSC1 expression decreased." (PMID 36539038, 2023). "Together, our study demonstrated that the RUNX2, NuRD(MTA1), and CRL4B complexes are physically associated and functionally linked to the promotion of EMT and bone metastasis of breast cancer cells." (PMID 35534547, 2022). "A study in breast cancer cells detected that MTA1, a highly deregulated oncogene involved in the stress adaptation of cancer, is an OGT substrate." (PMID 36291918, 2022). "These documented roles of MTA1 make it a valuable target to be explored in the metastatic colonization of breast cancer cells." (PMID 35496301, 2022).